CDH1 (cadherin 1)
Diseases named in the same sentence as CDH1 in open-access papers (continued):
Sharing a sentence is not in itself a finding about the gene and the disease.
leukemia (22 papers, 2012 to 2025). A malignant (clonal) hematologic disorder, involving hematopoietic stem cells and characterized by the presence of primitive or atypical myeloid or lymphoid cells in the bone marrow and the blood. "One study reported that dulaglutide induces demethylation of CDH1, the gene encoding E-cadherin—a cell adhesion molecule whose dysregulation has been implicated in certain leukemias." (PMID 41301540, 2025). "Since Skp2 protein expression is also increased in AML, we analyzed a potential additional role of Skp2 in Cdh1 degradation and found elevated Cdh1 levels in leukemia cells depleted of Skp2." (PMID 27374082, 2016). "Of note, CDH1 has previously been shown to be frequently methylated in various cancer types, including lymphoma and leukemia and functions as a tumor suppressor by inhibiting proliferation and invasion." (PMID 25226156, 2014). "However, further depletion of Cdh1 in APL significantly reduced viability of leukemia cells upon ATRA-induced differentiation." (PMID 27374082, 2016). "Cluster B near the center of the CIM is made up largely by leukemia lines, which exhibit low expression of both VIM and CDH1 and very low expression of most of the migration-related genes." (PMID 22570691, 2012). "Last but not least, the expression of E-cadherin (CDH1), the loss of which is considered the hallmark of EMT in solid tumors, is low in leukaemia due to the hypermethylation of its promoter." (PMID 30658474, 2019). "Expression of E-cadherin (Cadherin1:CDH1) gene, which is commonly methylated in ALL and CLL leukemia cells, is not detectable in lymphoid blasts." (PMID 28580304, 2017).
Lynch syndrome (22 papers, 2012 to 2025). An autosomal dominant hereditary neoplastic syndrome characterized by the development of colorectal carcinoma and a high risk of developing endometrial carcinoma, gastric carcinoma, ovarian carcinoma, renal pelvis carcinoma, and small intestinal carcinoma. "Germline mutations in E-cadherin (CDH1) or mismatch repair genes (Lynch syndrome) were identified many years ago but given their rarity, the identification of these molecular alterations does not substantially impact treatment in the advanced setting." (PMID 25784931, 2015). "Among these 45 patients, 11 out of the 16 with diffuse tumours fulfilled the HDGC criteria for testing the CDH1/CTNNA1 genes, and two of these 11 also fulfilled the criteria for Lynch syndrome (both with a pathogenic variant in the MLH1 gene)." (PMID 40446793, 2025). "Other, less common, gene mutations include CHEK2, PALB2, CDH1, MLH1 (associatedwith Lynch syndrome), and RET." (PMID 38993971, 2024).
inflammatory bowel disease (20 papers, 2015 to 2024). A spectrum of small and large bowel inflammatory diseases of unknown etiology. "CDH1 has also been identified as a susceptibility gene for inflammatory bowel disease and may increase the risk of Crohn’s disease and ulcerative colitis." (PMID 36371157, 2022). "Polymorphisms in E-cadherin, which is encoded by the CDH1 gene, are also associated with the pathogenesis of inflammatory bowel disease (IBD), suggesting that defects in the epithelial barrier and adherent junctions might contribute to the development of IBD." (PMID 26183215, 2015). "In the rat model of induced inflammatory bowel disease (IBD), expression of CDH1 and Cdh1 was decreased." (PMID 35267318, 2022). "More than 160 susceptibility genes predisposing to IBD so far have been identified, including inflammatory bowel disease 5 (IBD5) and cadherin 1 (CDH1) that are associated with epithelial barrier function (Miner‐Williams & Moughan, 2016)." (PMID 28283650, 2017).
mesothelioma (20 papers, 2011 to 2025). A usually malignant and aggressive neoplasm of the mesothelium which is often associated with exposure to asbestos. "A meta‐analysis has further revealed that the APC gene is significantly hypomethylated in mesothelioma, while CDH1, ESR1, miR‐34b/c, PGR, RARβ, SFRP1, and WIF1 are significantly hypermethylated." (PMID 40904706, 2025). "In our examples, tumor-selective mRNAs in the HNCs (EGFR, CDH1) were stable, however, mesothelioma-selective mRNAs (i.e., mesothelin and WT1) were reduced." (PMID 38744944, 2024). "A recent systematic review and quantitative meta-analysis of DNA methylation in mesothelioma found both significantly hypomethylated genes (APC) and hypermethylated genes (CDH1, ESR1, miR34b/c, PGR, RATO, SFRP1, and WIF1)." (PMID 38297314, 2024). "In this study, we investigated the relationship between CDH1 expression and the efficacy of FAK PND-1186, a potent and reversible inhibitor of FAK, in mesothelioma samples and in controls." (PMID 34638565, 2021).
laryngeal carcinoma (19 papers, 2011 to 2024). Carcinoma that arises from the laryngeal epithelium. "Other often methylated genes in laryngeal cancer include E-cadherin (CDH1), DAPK1, and p16 (CDKN2A)." (PMID 39452555, 2024).
oesophageal cancer (19 papers, 1995 to 2025). "Moreover, CDH1 (encoding E-cadherin) inactivating mutations or promoter hypermethylation in humans are associated with the development of gastric, prostate, hepatocellular, breast and esophageal carcinomas." (PMID 36421719, 2022).
Crohn disease (18 papers, 2010 to 2025). A gastrointestinal disorder characterized by chronic inflammation involving all layers of the intestinal wall, noncaseating granulomas affecting the intestinal wall and regional lymph nodes, and transmural fibrosis. "Importantly, the membrane-to-cytoplasmic delocalization of E-cadherin due to CDH1 polymorphisms is considered one of the main causes of epithelial failure in Crohn’s disease." (PMID 40284499, 2025). "Recently, polymorphisms in the CDH1 gene resulting in truncated and intracellularly mis-localized E-cadherin have been identified in patients with Crohn's disease." (PMID 21179475, 2010).
Alzheimer disease (17 papers, 2014 to 2025). A progressive, neurodegenerative disease characterized by loss of function and death of nerve cells in several areas of the brain leading to loss of cognitive function such as memory and language. "Downregulation of Cdh1 in post-mitotic neurons has been implicated in neurodegenerative diseases, such as Alzheimer’s disease." (PMID 28049433, 2017). "Here we show in neurons that oligomers of amyloid beta (Aβ), a peptide related to Alzheimer’s disease, cause proteasome-dependent degradation of cdh1." (PMID 27514492, 2016). "Besides, inactivation of Cdh1 has been implicated in excitation-mediated neuronal cell death in neurological disorders such as Alzheimer disease." (PMID 32117986, 2020). "This causes the aberrant accumulation of several anaphase promoting complex/cyclosome-Cdh1 targets in the damaged areas of Alzheimer’s disease brains, including Rock2 and Cyclin B1." (PMID 36588673, 2022). "Here we review the function of anaphase promoting complex/cyclosome-Cdh1 dysregulation in the pathogenesis of Alzheimer’s disease, paying particular attention in the neurotoxicity induced by its molecular targets." (PMID 36588673, 2022). "Interestingly, oligomerized amyloid-β (Aβ) peptide, which is involved in Alzheimer’s disease onset and progression, induces Cdh1 phosphorylation leading to anaphase promoting complex/cyclosome-Cdh1 complex disassembly and inactivation." (PMID 36588673, 2022). "Understanding the role of anaphase promoting complex/cyclosome-Cdh1-targeted substrates in Alzheimer’s disease may be useful in the development of new effective disease-modifying treatments for this neurological disorder." (PMID 36588673, 2022). "PANTHER pathways analysis of differentially expressed proteins revealed overrepresentation of Wnt signaling pathway (CDH1, CSNK2A2, GNA11, CTBP2, CDH17, SMARCE1, p-value 0.02), followed by Alzheimer disease-presenilin pathway (MMP8, MMP9, MLLT4, CDH1, P-value 0.04)." (PMID 29515771, 2018). "In Alzheimer’s disease and stroke pathogenesis, APC/CCdh1 but not Cdc20, is expressed in post-mitotic mammalian neurons and the inactivation of Cdh1 by phosphorylation results in the accumulation of cyclin B1." (PMID 33218190, 2020). "In Alzheimer’s disease and stroke pathogenesis, APC/CCdh1, but not APC/CCdc20, is expressed in post-mitotic mammalian neurons, and the inactivation of Cdh1 by phosphorylation results in the accumulation of cyclin B1." (PMID 33260674, 2020).
Obesity (17 papers, 2011 to 2025). Accumulation of substantial excess body fat. "GC is a complex, heterogeneous disease arising from unique epidemiologic backgrounds, such as Helicobacter pylori infection, diet, smoking, obesity, host genetic mutation and instability, such as E-cadherin gene (CDH1), PALB2, BRCA1, and RAD51C mutations." (PMID 35184134, 2022). "Risk factors, such as family history, diet, alcohol consumption, smoking, obesity, Helicobacter pylori infection, E-cadherin gene (CDH1) alteration, and polymorphisms of interleukin (IL-17 and IL-10) genes, are associated with a high incidence of GC." (PMID 33804393, 2021). "Immunohistochemistry for E-Cadherin (CDH1) showed an underdeveloped syncytiotrophoblast (SynT) within the labyrinth of HFD placentas compared to the CD group, suggesting a reduced maternal–fetal interface in the context of obesity." (PMID 39090270, 2024).
ulcerative colitis (17 papers, 2008 to 2025). An inflammatory bowel disease involving the mucosal surface of the large intestine and rectum. "In a recent study in the Netherlands, genetic testing was conducted on 821 patients with ulcerative colitis and 1260 healthy individuals and determined that rs1728785 of CDH1 was mutated, resulting in a 1.23-fold increased risk of ulcerative colitis." (PMID 36371157, 2022). "SRCC in the rectosigmoid has been associated with a history of ulcerative colitis, and methylation of the CDH1 promoter is seen in 93% of dysplastic biopsies compared to 6% of non-dysplastic biopsies in ulcerative colitis patients." (PMID 32545410, 2020). "Indeed, CDH1 encoding the epithelial cell marker E-cadherin is known to be reduced in areas of active ulcerative colitis." (PMID 25303049, 2014). "Furthermore, activating FGFR2 mutations occur in nondysplastic colorectal mucosa from ulcerative colitis patients, together with defects of the E-cadherin-encoding suppressor gene CDH1." (PMID 34007277, 2021).
adenomyosis (16 papers, 2015 to 2025). The growth of endometrial tissue inside the muscular wall of the uterine corpus. "An association has been noted between adenomyosis and the disruption of mechanisms involved in the transition from epithelial to mesenchymal cells, evidenced by reduced expression of the cadherin-1 (CDH1) protein and elevated levels of Notch and TGF-β." (PMID 39200389, 2024).
skin cancer (16 papers, 2005 to 2025). "In our study we observed an over-expression of CDH1 in skin cancer vs. normal skin, although a lower expression rate was expected." (PMID 16893473, 2006). "To clarify these apparent discrepancies on the role of IRF6 and GRHL3 in cancer, we screened breast, colon, lung, and skin cancer cell lines for IRF6, GRHL3, and CDH1 transcripts and compared their levels to them in corresponding control cell lines by qPCR." (PMID 36457487, 2022).
vitiligo (16 papers, 2021 to 2025). Generalized well circumscribed patches of leukoderma that are generally distributed over symmetric body locations and is due to autoimmune destruction of melanocytes. "This case-control study was conducted aiming to investigate the association between two single nucleotide polymorphisms (SNP) of CDH1 and susceptibility to develop vitiligo in a Mexican population: -347 G→GA (rs5030625) and -160 C/A (rs16260)." (PMID 36754648, 2023). "This is the first study of CDH1 rs503062 and rs16260 polymorphisms in vitiligo; an association between the AA genotype of CDH1 rs16260 and the risk of developing vitiligo was observed when compared to CC/CA genotypes." (PMID 36754648, 2023). "There is scarce information on polymorphisms of the e-cadherin gene CDH1 in vitiligo, eight polymorphisms have been previously studied and only the rs10431924 polymorphism showed an association with vitiligo." (PMID 36754648, 2023). "Variants close to the CDH1 gene have been associated with vitiligo in Brazilian individuals, linking defects in melanocyte adhesion to the pathogenesis of vitiligo." (PMID 35643735, 2022). "The CDH1 gene is also associated with susceptibility to vitiligo." (PMID 36235295, 2022). "We also examined the expression of Cadherin 1 (CDH1), a calcium-dependent cell-cell adhesion protein, which among others, anchors melanocytes to surrounding keratinocytes and is implicated in diseases such as vitiligo." (PMID 33793042, 2021).
astrocytoma (15 papers, 2004 to 2025). "Researchers have shown that a decrease in CDH1 expression is associated with astrocytoma progression, while other studies showed that high E-cadherin expression is associated with a poorer prognosis of the disease." (PMID 35216113, 2022). "A decrease in CDH1 expression is linked to astrocytoma progression." (PMID 36142368, 2022). "A recent report has found an increase of promoter hypermethylation in CALCA and CDH1 genes in high-grade astrocytomas, but they did not see any remarkable methylation frequency of other classical tumor suppressor genes, such as p14ARF, RB1, CDKN2B, or APC." (PMID 22389839, 2012).
blepharocheilodontic syndrome (15 papers, 2018 to 2026). An ectodermal dysplasia syndrome characterized by the association of abnormalities of the eyelids, lips, and teeth. "Blepharo-Cheilo-Dontic syndrome is predominantly inherited in an autosomal dominant manner due to mutations in the CDH1 and CTNND1 genes, which encode cadherin, a calcium-dependent cell adhesion molecule crucial for cell mobility and epithelial proliferation." (PMID 41563506, 2026). "According to the literature, congenital anomalies such as cleft lip/palate or blepharocheilodontic syndrome are frequently observed in some CDH1-mutation carriers." (PMID 41378303, 2025). "Blepharocheilodontic syndrome and nonsyndromic cleft lip/palate have also been related to CDH1 germline variants." (PMID 38796558, 2024). "Beyond HDGC predisposition, the CTNNA1 and CDH1 genes have been associated with macular dystrophy patterned and cleft lip/palate and blepharocheilodontic syndrome (BCD), respectively." (PMID 37686589, 2023). "In summary, we reported a novel heterozygous missense variant c.1198G>A (p.Asp400Asn) in the CDH1 gene in a Chinese family with BCD syndrome." (PMID 36552944, 2022). "We identified a novel heterozygous missense variant c.1198G>A (p.Asp400Asn) in the CDH1 gene in the proband and his mother with BCD syndrome." (PMID 36552944, 2022). "Recently, studies have identified that the pathogenic genes of BCD syndrome are cadherin 1 (CDH1) and catenin delta 1 (CTNND1)." (PMID 36552944, 2022). "Combining the clinical phenotype and genetic test results, we diagnosed the patients in this study with BCD syndrome caused by the CDH1 variant." (PMID 36552944, 2022). "CDH1 mutations have also been identified in patients with blepharocheilodontic syndrome, a congenital development disorder causing dysmorphic features, which can be accompanied by imperforate anus, hypothyroidism, and neural tube defect." (PMID 30568591, 2018). "After sonographic diagnosis of the bilateral cleft lip and palate and the persistent open eyelids, amniocentesis with subsequent molecular genetics confirmed the sonographically presumed de-novo mutation of the CDH1 gene and the Blepharo-Cheilo-Dontic Syndrome." (PMID 41563506, 2026). "However, heterozygous pathogenic CDH1 germline variants were reported in a few non-syndromic CL/P families, as well as in one syndromic form of CL/P: the blepharocheilodontic syndrome." (PMID 39596675, 2024). "The phenotype of CDH1-associated BCD syndrome also varied widely." (PMID 36552944, 2022). "This is the first report of CDH1-associated BCD syndrome in the Chinese population." (PMID 36552944, 2022). "In addition to cancer phenotypes, CDH1 variants are associated with Blepharocheilodontic syndrome (MIM: 119580) and cleft lip and palate (CLP)." (PMID 36246616, 2022). "However, the pathogenic mechanism of CDH1-associated BCD syndrome remains unclear and needs to be studied more extensively." (PMID 36552944, 2022). "A prior study of CDH1 variant data pooled from the literature and public genetic variation databases found that 13% of CDH1 variants were associated with syndromic CLP (only DGLBC and Blepharocheilodontic syndrome) and non-syndromic CLP." (PMID 36246616, 2022). "Missense mutations and rare variants in CDH1 were identified in patients with non-syndromic CL/P, patients with hereditary diffuse gastric cancer and CL/P, as well as in one of the syndromic forms of CL/P (blepharocheilodontic syndrome, BCDS)." (PMID 35205020, 2022). "Our results broaden the variation spectrum of BCD syndrome and phenotype spectrum of CDH1, which can help with the clinical diagnosis, treatment, and genetic counseling in relation to BCD syndrome." (PMID 36552944, 2022). "It is now widely known that in addition to diffuse gastric cancer (DGC) and lobular breast cancer (LBC), congenital malformations such as cleft lip/palate and BCDS (blepharocheilodontic syndrome) are a part of the spectrum of diseases associated with CDH1 deregulation." (PMID 31212809, 2019).
blepharocheilodontic syndrome (continued). "Our results broaden the variation spectrum of BCD syndrome and phenotype spectrum of CDH1, which could help with the clinical diagnosis, treatment, and genetic counseling of the disease." (PMID 36552944, 2022). "Notably, in humans, numerous mutations in genes encoding proteins of the adherens junction complex, including core components such as E-CADHERIN (CDH1) and P120-CATENIN (CTNND1), have been implicated in causing cleft lip as part of blepharocheilodontic syndrome and non-syndromic cleft lip." (PMID 41231213, 2026). "More recently, both germline and de novo pathogenic variants in CDH1 have also been shown to underlie both syndromic (blepharocheilodontic syndrome; BCDS) and non-syndromic forms of cleft lip with or without cleft palate (CL/P)." (PMID 32260281, 2020).
dysplasia (15 papers, 2012 to 2025). A usually neoplastic transformation of the cell, associated with altered architectural tissue patterns. "The expression of CDH1 in BE without dysplasia was similar to that in the squamous epithelium." (PMID 34818353, 2021).